HPN (hepsin)
Diseases named in the same sentence as HPN in open-access papers (continued):
Sharing a sentence is not in itself a finding about the gene and the disease.
gastric cancer (4 papers, 2016 to 2025). A primary or metastatic malignant neoplasm involving the stomach. "Testing gastric cancer models in hepsin-deficient mice should indicate the biological significance and the true molecular mechanism of hepsin in gastric cancer." (PMID 27841306, 2016). "Furthermore, we explored the association between hepsin expression and overall survival in gastric cancer patients with early or advanced clinical stages and with or without lymphatic metastasis and vascular invasion." (PMID 27841306, 2016). "The results demonstrated that hepsin expression in gastric cancer tissues is closely associated with histological differentiation (P = 0.001), Lauren classification (P = 0.001), T classification (P = 0.011) N classification (P = 0.039) and clinical stage (P = 0.007)." (PMID 27841306, 2016). "In addition, univariate and multivariate analyses showed that hepsin could be useful as an independent risk factor for poor prognosis in the 220 cases of gastric cancer." (PMID 27841306, 2016). "In the study, hepsin mRNA and protein expression level is mainly downregulated in Gastric cancer tissues." (PMID 27841306, 2016). "Our study aims to describe the expression pattern and evaluate the clinical implication of hepsin in gastric cancer patients." (PMID 27841306, 2016). "To further evaluate the prognostic value of hepsin in gastric cancer, we explored the correlation between hepsin expression and clinical data by Kaplan-Meier analysis and log-rank test." (PMID 27841306, 2016). "In order to obtain a more sensitive predictive model for outcomes of gastric cancer patients, we combined hepsin expression and TNM stage to create a prognostic score system." (PMID 27841306, 2016). "High expression of hepsin is correlated with poorer overall survival, as well as progression-free survival in patients with gastric cancer." (PMID 27841306, 2016). "According to Kaplan-Meier analyses, we found the overall survival is shorter in gastric cancer patients with high hepsin expression in all stages or in III–IV stage." (PMID 27841306, 2016). "In this study, we examined the hepsin expression pattern in gastric cancer and its relationship with clinicopathological characteristics." (PMID 27841306, 2016). "The result demonstrated that high expression of hepsin correlated to poorer overall survival as well as progression-free survival in gastric cancer patients." (PMID 27841306, 2016). "To this end, we have first time described the hepsin expression pattern in gastric cancer tissues in both protein and mRNA levels in this study." (PMID 27841306, 2016). "It will be helpful to compare expression levels of mRNA and protein of hepsin in tumor tissues with matched normal tissues of gastric cancer patients to describe the physiological and pathophysiological importance of hepsin in gastric cancer." (PMID 27841306, 2016). "Probably, gastric and gastric carcinoma cells use different signaling pathways in response to hepsin expression." (PMID 27841306, 2016). "Our findings reflect distinct actions of gastric and gastric carcinoma cells in response to hepsin protein." (PMID 27841306, 2016). "Also, an earlier study reported that Hepsin, a type II transmembrane serine protease, plays a role in advanced-stage gastric cancer, exhibiting significant expression differences in patients with progressed disease." (PMID 40909962, 2025). "High expression of hepsin was also found to be associated with poor overall survival in gastric cancer patients without vascular invasion or with lymphatic metastasis." (PMID 27841306, 2016). "Hepsin expression may contribute to gastric cancer progression and metastasis by a few molecular mechanisms." (PMID 27841306, 2016). "There is a significance between high hepsin expression and low hepsin expression in gastric cancer patients with advanced stage, III–IV, so we speculate that hepsin may contribute to gastric cancer in later stage." (PMID 27841306, 2016).
gastric cancer (continued). "The expression pattern and impact of hepsin in gastric cancer remain unclear, so we aim to investigate the correlation between hepsin protein and overall survival (OS) of gastric cancer patients." (PMID 27841306, 2016). "The Hepsin mRNA expression level was downregulated in 78% (39/50) of gastric cancer patients." (PMID 27841306, 2016). "Furthermore, we evaluated the hepsin expression by IHC in tissue microarray (TMA) containing 220 Gastric Cancer specimens." (PMID 27841306, 2016). "Because hepsin is upregulated in advanced stage of gastric cancer, it may contribute to expansion, growth, invasion and metastasis of these tumor cells." (PMID 27841306, 2016). "High hepsin expression in gastric cancer tissues may at some certain reflect the state of poorly differentiated gastric cancer cells." (PMID 27841306, 2016). "More importantly, Kaplan-Meier survival and Cox regression analyses were taken to access the prognosis of gastric cancer and predicted that hepsin protein expression was one of the significant and independent prognostic factors for overall survival of Gastric Cancer." (PMID 27841306, 2016). "In conclusion, our study has demonstrated that increased hepsin expression is correlated with poor prognosis in gastric cancer patients, and hepsin may be identified as an independent prognostic factor and may be a potential target for the treatment of gastric cancer patients." (PMID 27841306, 2016). "Recently, the significant therapeutic effect of SRI31215, a novel small molecule inhibitor of pro-HGF activation (inhibitor of hepsin, matriptase and HGF activator: similar function with HAIs), has been reported in MET-amplified non-small cell lung and gastric cancer cells." (PMID 40299447, 2025). "The mRNA expression of hepsin was analyzed in 50 gastric cancer and matched non-tumor tissues, which was downregulated in 78% (39/50) of gastric cancer." (PMID 27841306, 2016).
Obesity (4 papers, 2020 to 2023). Accumulation of substantial excess body fat. "Global HPN-KO mice are resistant to diet-induced obesity, and this lean phenotype is associated with enhanced glucose and lipid homeostasis." (PMID 36413406, 2023). "In mice, hepsin deficiency increases adipose browning and protects from high-fat diet-induced hyperglycemia, hyperlipidemia, and obesity." (PMID 37509434, 2023). "Hepsin‐deficient mice are resistant to obesity, hyperglycemia, and hyperlipidemia." (PMID 36967237, 2023). "Unlike WT mice, hepsin KO mice were protected from developing hyperlipidemia and obesity on a high-fat diet." (PMID 37509434, 2023).
prostate (4 papers, 2005 to 2025). "The functional importance of hepsin has been shown by its overexpression in a transgenic mouse model of prostate tumorigenesis, which led to basement membrane disorganisation and enhanced metastasis." (PMID 15928670, 2005). "Indeed, KLK14 presence was previously identified as a part of the prostate‐cancer‐related protease network, where secreted KLK14 and KLK4 are recruited to membrane protrusions decorated with cell surface‐bound hepsin and TMPRSS2." (PMID 40621923, 2025).
bladder cancer (3 papers, 2012 to 2025). "In addition, no apparent statistical correlation was also observed between the expression of HGF, MET, ST14, HPN, and HGFAC and the prognosis of patients with bladder cancer by GEPIA." (PMID 40299447, 2025).
squamous cell carcinoma (3 papers, 2011 to 2018). A carcinoma arising from squamous epithelial cells. "Type II transmembrane serine proteases comprises four subfamilies: (a) matriptase, (b) hepsin/transmembrane protease/serine (TMPRSS), (c) human airway trypsin-like (HAT)/differentially expressed in squamous cell carcinoma (DESC), and (d) corin." (PMID 29529050, 2018). "These are the matriptase subfamily, the hepsin/transmembrane protease serine (hepsin/TMPRSS) subfamily, the corin subfamily, and the human airway trypsin-like protease/differentially expressed in squamous cell carcinoma (HAT/DESC) subfamily." (PMID 21853097, 2011).
chronic lymphocytic leukemia (2 papers, 2019 to 2023). "The toxicity of these compounds has yet to be tested in humans, while the calculated 2xIC50 of venetoclax for hepsin is within the concentration range tested in chronic lymphocytic leukemia cells." (PMID 37275957, 2023).
lung adenocarcinoma (2 papers, 2014 to 2019). A carcinoma that arises from the lung and is characterized by the presence of malignant glandular epithelial cells. "The analyses of TCGA database revealed that matiptase is down-regulated in the high-risk group with a low survival rate in lung adenocarcinoma patients, while hepsin levels is not relevant with the lung cancer patients’ survival (both low-risk and high-risk groups have a similar survival rate)." (PMID 30765871, 2019).
lung carcinoma (2 papers, 2017 to 2019). "The levels of matriptase and hepsin, two of the pro-HGF converting enzymes, are significantly elevated in lung cancer compared to normal lung tissue." (PMID 28968967, 2017).
lymph node metastasis (2 papers, 2007 to 2014). "In that model, LnCaP-34 cells displayed a Hepsin-dependent ability to invade and develop lymph node metastasis." (PMID 24657880, 2014).
metastatic cancer (2 papers, 2022 to 2025). A carcinoma which has spread from the original site of growth to another anatomic site. "The gene HPN has been associated with tumor invasion and metastasis, while the androgen receptor (AR) gene is crucial in promoting metastatic cancer progression." (PMID 40034593, 2025). "In addition, in metastatic cancer, HPN expression in the primary tumor appears to be subjected to paradoxical regulation in the processes of tumor differentiation and invasion of distant organs." (PMID 35804878, 2022). "In this sense, in patients with metastatic cancer, by considering only the expression of HPN in the primary tumor, we could be underestimating the total levels of HPN in the time-to-event analysis." (PMID 35804878, 2022).
prostate adenocarcinoma (2 papers, 2011 to 2025). "The introduction of Anthralin into lysated human prostate adenocarcinoma cells caused a 50–70% reduction in the general proteolytic activity, which attests to the fact that anthralin has an efficient inhibiting action on native hepsin localized on the membranes of tumor cells." (PMID 22649671, 2011). "The expression level of hepsin was shown to considerably increase on the surface of prostate adenocarcinoma cells." (PMID 22649671, 2011). "The main contribution to proteolytic activity on the surface of prostate adenocarcinoma cells is made by hepsin, since it is its gene that is over-expressed." (PMID 22649671, 2011). "The volcano plot indicated significant upregulation of genes such as SIM2, HPN, and HOXC6 in prostate adenocarcinoma (PRAD), and significant downregulation of genes such as SLC39A2, SLC39A6, and SLC39A10." (PMID 40978029, 2025).
bacteremia (1 paper, 2019). "The second bacterial candidate for HpN group in our study was Haemophilus parainfluenzae, which is an opportunistic pathogen responsible for several infections, including the respiratory tract infections, endocarditis, bacteremia and sepsis." (PMID 30974798, 2019).
diabetes (1 paper, 2019). "Index SNPs at CUBN and HPN (Hepsin) showed larger effect sizes among those with diabetes compared with the overall sample." (PMID 31511532, 2019).
endometriosis (1 paper, 2019). The growth of functional endometrial tissue in anatomic sites outside the uterine body. "Concentration of seven analytes (ALDH1A, CA9, CD44, hepsin, midkine, TGM2, and kallikrein-6) differed in endometriosis samples as compared to control samples and levels of five markers (ALDH1A, CA9, CD44, hepsin, and midkine) were different between endometriosis and EC samples." (PMID 31035965, 2019). "Significant differences were encountered between endometriosis and EC in case of five analytes, of which all were increased: ALDH1A (p = 0.019), CA9 (p = 0.031), CD44 (p = 0.010), hepsin (p = 0.007), midkine (p < 0.001)." (PMID 31035965, 2019).
gastric tumor (1 paper, 2016). "Evidence was presented that hepsin protein expression was mainly located in the nuclear and cytoplasm of gastric tumor cells, peritumoral tissue cells and normal tissue cells." (PMID 27841306, 2016). "The IHC density of hepsin exhibits a significant difference in gastric tumor tissues and their matched adjacent non-tumor tissues (P < 0.001)." (PMID 27841306, 2016).
injury (1 paper, 2024). Damage inflicted on the body as the direct or indirect result of an external force, with or without disruption of structural continuity. "Emerging as a promising therapeutic target, hepsin holds potential for combination therapy with N-acetylcysteine, paving the way for novel approaches in managing drug-induced liver injury." (PMID 39292286, 2024).
Insulin resistance (1 paper, 2015). Increased resistance towards insulin, that is, diminished effectiveness of insulin in reducing blood glucose levels. "Furthermore, this study also explores the role of HPN in insulin resistance induced by PA and the possible molecular mechanisms underlying PA-induced cell damage and insulin resistance in HepG2 cells." (PMID 26193288, 2015).
insulinomas (1 paper, 2015). "An interesting finding of the present study was the absence of RNA expression of HGFAC, considered the most powerful activator of pro-HGF in HGF, indicating that in insulinomas, matriptase (and maybe other proteins not evaluated in this study, such as hepsin) is responsible for pro-HGF proteolysis." (PMID 26435753, 2015).
Iron deficiency anemia (1 paper, 2023). "Hepsin is associated with some diseases, especially cancer, while TMPRSS6 is mainly involved in iron metabolism and iron deficiency anemia." (PMID 37888440, 2023).
laryngeal carcinoma (1 paper, 2024). Carcinoma that arises from the laryngeal epithelium. "A similar distribution pattern of hPn-ASV expression in the stroma has been observed in many cancer types, including ovarian and laryngeal cancer." (PMID 39334860, 2024).
phospholipidosis (1 paper, 2024). "Additionally, the downregulation of FABP1, HPN, and SERPINA3 genes is related to phospholipidosis." (PMID 38992651, 2024).
renal carcinoma (1 paper, 2022). A carcinoma arising from the epithelium of the renal parenchyma or the renal pelvis. "Previous studies have shown that hepsin expression is increased in several types of solid cancers, such as prostate, breast, ovarian, and renal cancers, including different studies using small-sized human samples, as addressed above." (PMID 35204704, 2022).
sarcoma (1 paper, 2014). A usually aggressive malignant neoplasm of the soft tissue or bone. "Hepsin (HPN) is a cell surface serine protease amplified in a subset of human sarcomas (7.2%), as well as in ovarian (10%), lung adeno (5.4%), lung squamous cell (4.5%), adenoid cystic (5%), breast (2.6%), uterine (1.7%) and colon (1.4%) carcinomas." (PMID 24657880, 2014).
synovitis (1 paper, 2017). Inflammation of a synovial membrane. "As hepsin gene expression is responsive to pro-inflammatory cytokines, and correlates with synovitis from human OA patients, we conclude that hepsin may have a role in cartilage destruction that has a more inflammatory phenotype." (PMID 29196708, 2017).
thrombosis (1 paper, 2023). "In the Fine-Gray regression, continuous hepsin (log-transformed) was associated with more thrombosis with a sub-hazard ratio of 2.12 (95% CFI, 1.50–2.98)." (PMID 37275957, 2023). "Subjects with a logarithm of hepsin concentration >Q3 (7.4 pg/mL) had a 24-month thrombosis CI of 34.7% (95% CFI, 0.2-86) compared to zero events in subjects with levels ≤Q3 (p-value = 0.036, Gray test)." (PMID 37275957, 2023).
Tinnitus (1 paper, 2021). Tinnitus is an auditory perception that can be described as the experience of sound, in the ear or in the head, in the absence of external acoustic stimulation. "Indeed, we observed evidence for blast-induced elevations in GAP43 levels in the DCN (and NAC/HPN-07-specific mitigation) at nine weeks post-exposure, which has intriguing implications for tinnitus-related maladaptive plasticity in the DCN." (PMID 33411811, 2021).
Type 2 diabetes (1 paper, 2013). "HPN therefore have potential for development as treatments for Type 2 diabetes." (PMID 23364683, 2013).